MALT1 (MALT1 paracaspase)
Diseases named in the same sentence as MALT1 in open-access papers (continued):
Sharing a sentence is not in itself a finding about the gene and the disease.
infection (continued). "Notably, our study observed morphological changes in macrophages post-infection, along with upregulation of key NF-κB pathway genes (Nfkb1, Nfkb2, Tnf, and Malt1), further establishing F. nucleatum’s contribution to an immunosuppressive TME in CRC." (PMID 40248690, 2025). "The latest research shows that PRRSV modulates mucosa-associated lymphoid tissue lymphoma translocation protein 1 (MALT1) expression to antagonize anti-PRRSV RNases N4BP1 and monocyte chemotactic protein-induced protein (MCPIP1) upon infection, thereby facilitating viral replication." (PMID 37007469, 2023). "In the present study, we hypothesized that the suppressed levels of MCPIP-1 and elevated levels of MALT-1 in human gingival tissues are related to the extension of infection (P. gingivalis colonization) and severity of clinical inflammation." (PMID 37010640, 2023). "Treatment of proteasome inhibitor MG-132 and co-IP analysis confirmed that MALT1 was degraded via the ubiquitin-proteasome pathway at the late infection stage, and PRRSV nsp6 could independently mediate this process." (PMID 35467421, 2022). "Transfer of immune serum was unable to rescue the MALT1−/− mice from lethal infection." (PMID 29367251, 2018). "PJP is a very common infection in CARD11 deficiency (reported in 75% of identified patients) but is not a reported pathogen in MALT1 and BCL10 deficiency." (PMID 30283440, 2018). "Together, PRRSV nsps may accurately modulate MALT1 expression at different infection states." (PMID 35467421, 2022). "With small molecule inhibitors, the inhibition of MALT1 pathway will be partial, and can be titrated based on dose and dose frequency, and thus we believe that the infection risk related to pharmacological MALT1 inhibitors may not be a significant problem." (PMID 32870913, 2020). "Elevated expression of MALT1 and TNF, two critical mediators of NF-κB signaling, reflects enhanced cellular responses to infection, potentially amplifying immune and inflammatory processes in RAW264.7 cells." (PMID 40248690, 2025). "The results showed that MALT1 overexpression significantly upregulated virus titers in the culture supernatant and PRRSV-N protein levels in infected cells during a 36-h infection course." (PMID 35467421, 2022). "The results showed that in Marc-145 cells, MALT1 was elevated until 48 h after PRRSV infection at an MOI of 0.1, whereas upon infection at an MOI of 10, MALT1 expression reached its peak at 12 hpi and subsequently decreased." (PMID 35467421, 2022). "Finally, several pro-apoptotic genes, including Bcl3, Bcl10, Malt1 and Dedd2, were up-regulated in response to muriform cells infection whereas Bcl2l12, coding to anti-apoptotic factor, was down-regulated, suggesting that infection of macrophages with muriform cells could induce apoptosis." (PMID 28355277, 2017). "Next, we studied MALT1 expression after TIFA reconstitution in SK-Hep1-TIFA and HepG2-TIFA cell lines at 24 h, 48 h and 7 days post infection versus controls using western blot analysis." (PMID 29263897, 2016). "Beyond that, decreased PBMC MALT1 expression was correlated with the occurrence of G‐ bacteria‐primary infection (Z = −2.047, p = 0.041) but not correlated with primary infection sites or other primary organisms (all p > 0.05)." (PMID 35262976, 2022). "For their part, pro-inflammatory cytokines triggered by CARD9/Bcl-10/MALT1 below Syk were not impacted by CR3-mediated infection with rBCG::PGL-I." (PMID 31921172, 2019). "The presence of CD169+ cells in spleen tissue was not affected by Malt1 before or after infection with VSV." (PMID 29142134, 2018). "Infection of Nestin-Cretg/+ MALT1FL/FL and LysMCretg/+ MALT1FL/FL mice yielded survival results comparable to those of wild-type littermates, excluding a role for MALT1 in neurons, astrocytes, oligodendrocytes, or myeloid cells." (PMID 29367251, 2018). "In contrast, mice lacking MALT1 specifically in neuroectodermal cells or myeloid cells survived the infection." (PMID 29367251, 2018).
infection (continued). "Our results demonstrate that MALT1 plays an important role in the control of infection by attenuated rabies virus in the CNS of laboratory mice by inducing neuroinflammation and by recruiting and activating CD8+ and CD4+ T cells within the brain in the early phase of infection." (PMID 29367251, 2018). "In contrast to wild-type littermates (CD4-Cre+/+ MALT1FL/FL), infection of T cell-specific MALT1−/− mice (CD4-Cretg/+ MALT1FL/FL) with ERA virus led to severe disease and death between 15 and 17 dpi, similarly to the phenotype observed in MALT1 full-knockout mice." (PMID 29367251, 2018). "The MALT1 inhibitor also did not affect the macrophage’s production of IL-6 and TNFα following L. pneumophila infection whether examined at the early 9-h time point or at 12, 24, and 48 h post infection." (PMID 34280250, 2021). "Mice specifically lacking MALT1 in myeloid cells (LysMCretg/+ MALT1FL/FL) or cells of neuroectodermal origin (neurons, astrocytes, or oligodendrocytes; Nestin-Cretg/+ MALT1FL/FL) were therefore also generated and analyzed in similar infection experiments." (PMID 29367251, 2018).
hematological cancers (2 papers, 2022 to 2026). "MALT1 inhibitors are currently being investigated in a handful of early phase clinical trials (e.g., ClinicalTrials.gov identifier: NCT04876092, NCT04859777, NCT05144347) in solid and hematological cancers, however, their therapeutic potential in autoimmune inflammatory diseases remains untested." (PMID 35615349, 2022).
hematological malignancies (1 paper, 2022). "Here, we review the molecular features of MALT1 activation and function as well as the therapeutic potential of MALT1 inhibition in hematological malignancies and solid tumors." (PMID 35203553, 2022). "Here, we will summarize what is known about the molecular function of MALT1 and how it is activated in hematological malignancies and solid cancers, and discuss the therapeutic potential of MALT1 inhibitors as well as their impact on immunotherapy." (PMID 35203553, 2022). "At present, it is broadly accepted that constitutive activation of MALT1 by either genetic alterations, chronic antigen receptor signaling, overexpression, or viral proteins drives the development of several hematological malignancies." (PMID 35203553, 2022).
neurodegenerative disease (1 paper, 2025). A disorder of the central nervous system characterized by gradual and progressive loss of neural tissue and neurologic function. "Despite extensive research in these contexts, the role of MALT1 in neuroinflammation and neurodegenerative diseases, including AD, remains largely unexplored." (PMID 41567547, 2025). "However, research on MALT1 in CSF and brain tissue remains limited in AD, and its precise role in neuroinflammation and neurodegenerative diseases is not fully understood." (PMID 41567547, 2025).
MALT1 also shares sentences with these, for which no sentence is quoted: mantle cell lymphoma (6 papers); atopic dermatitis (4); pancreatic cancer (3); acquired immune deficiency syndrome (2); acute lymphoblastic leukemia (2); Alzheimer disease (2); angioimmunoblastic T-cell lymphoma (2); gastric lymphoma (2); hypogammaglobulinemia (2); lung adenocarcinoma (2); multiple myeloma (2); osteosarcoma (2); periodontal disease (2); T-cell lymphomas (2); acute myeloid leukemia (1); adenocarcinoma (1); ataxia telangiectasia (1); autism (1); brain injury (1); breast DLBCL (1); bronchiectasis (1); Burkitt lymphoma (1); chronic granulomatous disease (1); colon adenocarcinoma (1); common variable immunodeficiency (1); COVID-19 (1); diabetes (1); duodenitis (1); encephalitis (1); endometrial cancer (1).
A further 39 diseases each share a sentence with MALT1 in 1 paper.